VIM (vimentin)
Diseases named in the same sentence as VIM in open-access papers (continued):
Sharing a sentence is not in itself a finding about the gene and the disease.
cancer (continued). "Recently, vimentin has emerged as a signaling platform of a number of critical proteins at the cell surface, which contribute to the invasive phenotypes of cancer, E. coli-induced pathogenicities, and cell signaling." (PMID 22536447, 2012). "In several studies, more than 90% of the basal-like carcinomas were found to have diffuse and strong vimentin expression." (PMID 23082819, 2012). "The proportion of double-positive CTCs in early stage cancer patients was 53% and 56% for Twist and vimentin, respectively, which was also significantly different from metastatic breast cancer patients (P = 0.0001 and P = 0.05, respectively)." (PMID 21663619, 2011). "Vimentin is an intermediate filament of mesenchymal cells that is commonly used to identify cells undergoing EMT in cancer." (PMID 21663619, 2011). "The median expression of Twist and vimentin was also significantly lower (40.6% and 55.6%, respectively) in early stage cancer patients, but it was extremely variable from patient to patient (ranges, 11% to 100% and 21% to 100%, respectively)." (PMID 21663619, 2011). "Although IF is only semi-quantitative, it clearly revealed very strong Vimentin expression in CA1a high grade cancer cells compared to 10A1 normal mammary epithelial cells." (PMID 20543960, 2010). "The de novo expression of vimentin is frequently involved in the epithelial-to-mesenchymal transition (EMT) associated with increased invasive/migratory properties of epithelial and cancer cells." (PMID 21317457, 2010). "The resultant tumors display lumen-like morphology, contain carcinoma-like focal areas with intercellular junctions resembling desmosomes, and co-express epithelial (cytokeratin) and mesenchymal (vimentin) cytoskeletal markers." (PMID 20591135, 2010). "In high-grade dysplastic cervical cells filamin, vimentin and vinculin were upregulated in contrast to the findings in cancer cells in our study." (PMID 19367286, 2009). "Elevated vimentin expression level correlates well with up-regulated migration and invasion of cancer cells." (PMID 19695088, 2009). "This can be explained at least partially by correlation of vimentin expression with ER and PgR negativity, and with higher grade of cancer." (PMID 19695088, 2009). "Of the antigens reported herein, only vimentin had been reported as an antigen in cutaneous lymphoma before, the other 13 are new for this type of cancers." (PMID 20020065, 2009). "Vimentin is a type III intermediate filament protein that is frequently expressed in epithelial carcinomas and correlates with invasiveness and poor prognosis." (PMID 19367286, 2009). "In the patient we have described, as well, the overt carcinoma cells were positive for vimentin, S-100 protein and cytokeratins (AE1/AE3, CK7, CK8 and CK19)." (PMID 18559079, 2008). "Vimentin protein expression levels were investigated by comparing the integrated intensity of spots visualized in 2-D PAGE gels of various cancers." (PMID 18769604, 2006). "Epithelial-mesenchymal transition (EMT) is considered a mechanism for carcinoma progression and metastasis, and the expression of vimentin (VIM) is its main marker." (PMID 16626496, 2006). "Upon further molecular characterization of cancer hallmark biomarkers, we found a downregulation of the expression of cell–cell adherens junction transmembrane protein E-cadherin and upregulation of EMT marker vimentin as indicators of metastatic capacity." (PMID 41407936, 2026). "Moreover, curcumin reversed aniline-induced EMT via the ERK5/AP-1 pathway, causing an increase in E-cadherin expression and a decrease in Vimentin expression, thus inhibiting cancer cell invasion." (PMID 41596251, 2026). "Differential gene expression analysis showed overexpression of classic epithelial genes (for example, SFTPC and STEAP1), genes associated with cancer (for example, CLDN6) and regulators of EMT (for example, VIM, FN 1 and CDH2) in Oncopig LC versus normal pig lung tissues." (PMID 41407936, 2026).
cancer (continued). "With the identification of two separate immune responses in cancer patients to vimentin, pritumumab and RM2, all derived from sentinel LNs, strongly suggests that there may be other patients that also mount an immune response to cell surface vimentin (EDV)." (PMID 40051499, 2025). "For instance, inhibiting BMP-2 or vimentin could sensitize cancer cells to existing therapies or prevent metastatic spread." (PMID 39859358, 2025). "To determine whether PRMT1‐mediated cancer cell migration requires vimentin, we performed wound healing assays." (PMID 40884268, 2025). "Vimentin was detected with both cancer types, but with a higher prevalence in patients with PDAC." (PMID 40806708, 2025). "Vimentin’s interaction with the PI3K/AKT pathway is significant in cancer progression and EMT." (PMID 40229242, 2025). "Moreover, we also found an increased apoptosis of cancer cells, endothelial cells, and fibroblasts, and reduced expression of the mesenchymal markers, such as vimentin and PDGFR." (PMID 39985042, 2025). "Furthermore, co-culture with cancer cells disrupted cytoskeletal homeostasis in adipocytes, which enhanced the formation of actin filaments and led to the development of a more complex vimentin network." (PMID 41353220, 2025). "Differential gene expression analysis showed overexpression of classic epithelial genes (e.g., SFTPC and STEAP1), genes associated with cancer (e.g., CLDN6), and regulators of EMT (e.g., vimentin, fibronectin 1, and N-cadherin) in Oncopig LC versus normal pig lung tissues." (PMID 39975891, 2025). "STAT3 is widely recognized as a therapeutic target in multiple cancers and has been shown to transcriptionally regulate key effector proteins such as cyclin D1, vimentin, and survivin, which are critically involved in cell proliferation, migration, and apoptosis." (PMID 41476794, 2025). "It is also expressed in high-grade cancer cells, forming copolymerized filaments with vimentin." (PMID 39851565, 2025). "Carcinoma HepG2 cell transfected high expression of HSP90can promote the transformation of EMT, improve the expression of Vimentin, reduce the expression of E-cadherin, and inhibit apoptosis of cancer stem cells, which improve the invasive ability of cancer of the liver cells." (PMID 41186893, 2025). "Consistent with reported downstream effects of HER4 inhibition, KAE treatment also induced a moderate to strong reduction in the expression of adhesion and motility proteins, such as vimentin and cadherin, which are highly relevant in cancer cell dissemination." (PMID 41515404, 2025). "RPPA analysis further indicated that macrophage-derived exosomes induced changes in the expression levels of several proteins associated with aggressive characteristics in cancer cells, including MAPK (ERK), vimentin, AMPKa, eIF4G, STAT3, and B-Raf in PANC-1 cells." (PMID 40624025, 2025). "In the examined cancer cells, it forms copolymerized filaments with vimentin." (PMID 39851565, 2025). "Next, we examined whether cancer cells were present in the CD45-Vimentin+ fraction by cytological examination." (PMID 40718490, 2025). "We next examined the proportion of cancer cells within the CD45-Vimentin+ fraction (CTC fraction)." (PMID 40718490, 2025). "During EMT, cancer cells lose their epithelial features due to a reduction in cell–cell adhesion molecules like E-cadherin, and they acquire mesenchymal phenotypes characterized by increased levels of proteins such as N-cadherin, vimentin, and fibronectin." (PMID 40806251, 2025). "In addition to E-cadherin and ß-catenin, TPM’s ability to downregulate vimentin expression implies that it can prevent the mesenchymal transition of cancer cells, reducing their motility and invasive capabilities." (PMID 40283503, 2025). "Furthermore, fibroblasts exposed to CC cells typically undergo conversion to cancer-associated fibroblasts (CAFs), as evidenced by increased CAF markers (e.g., ACTA2, FAP, COL1A2, VIM)." (PMID 40055606, 2025).
cancer (continued). "Vimentin has also been shown to play an important role in the promotion of cancer cell migration." (PMID 39937011, 2025). "Some of these changes could be reversed by RNAi-mediated downregulation of vimentin establishing a direct link between residue 328 of vimentin, or perhaps the surrounding region, in cancer progression, which is a novel finding." (PMID 40690373, 2025). "Given that M2 macrophages are known to induce epithelial‐mesenchymal transformation (EMT) in cancer cells, we explored the correlation between VSIG4 and several biomarkers associated with EMT processes (MMP9, SNAI1, SNAI2, VIM, TWIST1, TWIST2, CDH1, CDH2) in CRC through the TIMER2.0 website." (PMID 40405491, 2025). "Furthermore, vimentin filaments play a crucial role in protecting cancer cells from mechanical stresses encountered during migration or when squeezing through confined spaces." (PMID 40830621, 2025). "VIM was known as a potential cancer therapeutic target, and reports found that VIM could promote the invasion and metastasis of CRC cells by binding to overexpressed FSTL1." (PMID 40864806, 2025). "Beyond cancer, vimentin plays essential roles in multiple biological systems." (PMID 40618999, 2025). "On the other hand, we examined the expression of the mesenchymal markers desmin and vimentin and found that the levels of both proteins were suppressed in the BNE-RRC-treated cancer cells, indicating the loss of MET in these cancer cells under the treatment with BNE-RRC." (PMID 39273519, 2024). "We integrated analyzed the function of P4HA3 among 33 types of cancers, and found that P4HA3 was associated with proliferation markers (PCNA and MKI67), EMT markers (VIM, TWIST1, SNAI1, SNAI2, FN1 and CDH2), extracellular matrix (ECM) markers (MMP9, MMP7, MMP2 and MMP14)." (PMID 39504328, 2024). "Inhibition of PAK1, the primary downstream target of Rac1 responsible for vimentin Ser38 phosphorylation greatly reduced metastasis, highlighting a promising potential for developing drugs targeting this function for cancer treatment." (PMID 38915055, 2024). "Cancer cells exhibited high vimentin positivity more frequently than YK-1–3 cases (p < 0.0001)." (PMID 38444414, 2024). "Accordingly, GKN1+ ECs, MUC1+ ECs, and VIM+ ECs were regarded as cancer cells." (PMID 39422697, 2024). "Collectively, these studies support the hypothesis that VIM and CK co-expression is beneficial for cancer progression." (PMID 39766058, 2024). "Additionally, another study demonstrated that PEVs from patients with colorectal cancer induced Twist1 and vimentin expression in all cancer cell lines studied, whereas PEVs from healthy controls did not." (PMID 39183323, 2024). "Vimentin, a prominent constituent of the intermediate filament, exhibits selective expression in healthy MSCs, while its expression is significantly upregulated in different cancer types." (PMID 38703300, 2024). "Vimentin therefore serves a mesenchymal marker during the EMT process in cancer cells." (PMID 38311781, 2024). "If this hypothesis is proven to be correct, blocking vimentin Ser38 phosphorylation would impair the survival of circulating tumors and could potentially serve as a cancer metastasis prevention strategy." (PMID 38915055, 2024). "Vimentin positioning mediated by vesicular trafficking machinery, which in turn affects key endosome functions that regulate migratory factors, appears to be a critical determinant for cancer cell migration." (PMID 39796673, 2024). "In vitro wound-healing assays have shown that disrupting vimentin blocks directional migration and delays wound healing in several different cell types, including mEF, primary astrocytes, retinal pigment epithelial cells and polyploidal giant cancer cells." (PMID 38835244, 2024). "It has long been established that various cancer cells may overexpress vimentin in order to facilitate epithelial-mesenchymal transition and enhance metastatic cell growth." (PMID 39123440, 2024).
cancer (continued). "Our findings contradict the previously reported function of vimentin in cancer, suggesting that vimentin may have a tissue-specific function in the endometrium." (PMID 39516342, 2024). "USP14 removes ubiquitin from vimentin to promote cancer in gastric cells." (PMID 39605891, 2024). "Specifically, the mEVs from CRC patients caused an increase in the expression of TWIST1 and VIM (protein name: vimentin) in all the studied cancer cell lines, while those from healthy subjects did not." (PMID 39764464, 2024). "The protein expression level of VEGF, E-cadherin, Vimentin, p-PI3k, p-Akt, and p-mTOR in the cancer cells treated by HDAC inhibitor was significantly reduced compared with the drug-resistant group, along with significantly increased expression level of E-cadherin (P<0.05)." (PMID 38645502, 2024). "Furthermore, combined administration of SBE with HSP90β siRNAs showed synergistic effects in the diminishment of vimentin by activating ubiquitination, which triggers the changes in cell shape, adhesion, and motility during cancer progression." (PMID 38474318, 2024). "Moreover, the protein and mRNA expression levels of vimentin and snail were reduced, whereas the opposite result was confirmed for E-cadherin expression in the Cat D siRNA-transfected cancer cells." (PMID 38297161, 2024). "APC-labelled anti-CD45mAB was used to gate remaining hematogenous cells, while multiple epithelial markers (EpCAM, EGFR, and Pan-Cytokeratin) and an epithelial–mesenchymal transition (EMT) marker (Vimentin) labelled with fluorescein isothiocyanate (FITC) were used to sort cancer cells." (PMID 38469233, 2024). "Moreover, these transcription factors induce the expression of mesenchymal genes such as N-cadherin or vimentin, which promote cancer cell invasiveness, cytoskeleton, cell mobility and focal adhesions." (PMID 38255995, 2024). "In comparison with the HDAC inhibitor treatment, VEGF, Vimentin, p-PI3k, p-Akt, and p-mTOR protein expression levels were significantly decreased in the cancer cells treated by HDAC inhibitor+PI3K inhibitor; while E-cadherin protein level was significantly increased (P<0.05)." (PMID 38645502, 2024). "Other and our studies suggest that the strategies to inhibit vimentin’s expression, assembly, or perinuclear accumulation in cancer cells may ameliorate their malignancy." (PMID 39542246, 2024). "During the process of EMT, cancer cells progress to malignancy and obtain migration ability to invade other areas, with a decrease in epithelial cell adhesion proteins such as E-cadherin and mesenchymal markers such as N-cadherin and Vimentin." (PMID 38178023, 2024). "Consistently, VEGF activates actin filament polymerization, vimentin expression, and invadopodium formation at the migrating front of cancer cells in the same way in which it promotes the budding of a podosome from the surface of endothelial cells during angiogenesis." (PMID 39120324, 2024). "On the other hand, VIM+ CAFs may facilitate the EMT function of MUC1+ cancer cells through the MK pathway." (PMID 39422697, 2024). "Furthermore, the use of an inhibitor of p21-activated kinase PAK1, one of the kinases responsible for vimentin Ser38 phosphorylation, significantly reduced cancer metastasis in animal models." (PMID 38915055, 2024). "In general, vimentin expression increases the migration and invasion of cancer cells." (PMID 38474590, 2024). "Vimentin is an IF protein expressed in mesenchymal cells and highly invasive cancer cells." (PMID 38835244, 2024). "Using scRNA-seq data, we investigated the expression of genes involved in stromal-like signature (FAP, VIM, and ITGB1); cancer-associated fibroblasts (CAFs; POSTN and ACTA2); as well as COL1A1, SULF1, TCF21, and DLK1, which were previously associated with FAP-high or FAP-low CAF phenotypes in OC." (PMID 39634630, 2024).
cancer (continued). "In addition, while Vimentin expression was most frequently detected in stromal cells of G2 cSCCs, it was also expressed in mesenchymal Ecad−Vim+ cancer cells of G3 cSCCs and, at high level, in G4 cSCC cancer cells." (PMID 38914547, 2024). "Previous studies pointed to an up-regulatory effect of M2 TAMs and TAFs on the expression of IL-10 and TGF-β, IL-6 and MMPs, and the endothelial mesenchymal transition (EMT)-related genes, e.g., vimentin in cancer cells which subsequently dampened the efficacy of ICD." (PMID 37612575, 2024). "Overexpression of vimentin has been shown to promote the recycling of integrins and cell migration, suggesting that overexpression of vimentin in cancer cells may increase the endosomal recycling of migratory factors." (PMID 39796673, 2024). "In the early stages of cancer, vimentin is at a very low level." (PMID 38540190, 2024). "Vimentin is a hallmark marker of epithelial-to-mesenchymal transition (EMT), a cellular process associated with increased cell motility, invasiveness, and meta-static potential in cancer." (PMID 38790277, 2024). "In addition to its anti-cancer properties, BNE-RRC can reverse the EMT in cancer cells by suppressing mesenchymal markers, such as desmin and vimentin, and increasing the expression of the MET marker α-catenin." (PMID 39273519, 2024). "In the context of cancer cells, changes in the expression or structure of vimentin may affect their function." (PMID 38611032, 2024). "Suppression of VIM expression hinders carcinoma cells' attachment and migration." (PMID 40259961, 2024). "The co-expression of CKs and VIM is a feature of aggressive carcinomas." (PMID 39766058, 2024). "To this end, we will discuss what is known regarding the structure and function when CK and VIM are co-expressed in hybrid E/M cells and provide our perspective to suggest how these traits could influence carcinoma progression." (PMID 39766058, 2024). "In CC HPV+ cell lines, the potassium voltage-gated channel subfamily C member 4 (KCNC4 or Kv3.4) and the AKT pathway have been shown to regulate vimentin expression, and the use of blood depressing substance II (BDS-II) as a channel blocker decreases vimentin expression and cancer cell migration." (PMID 37408210, 2023). "Consequently, vimentin contributes to several pathophysiological conditions such as cancer, autoimmune and inflammatory diseases, or infection." (PMID 37475865, 2023). "Vimentin and keratin are an interesting pair of intermediate filaments, as the “switch” between them plays a major role in the epithelial-to-mesenchymal transition and, therefore, in cancer mestastasis, wound healing, and embryogenesis." (PMID 37332398, 2023). "EMT is a vital step for the facilitation of a malignant and invasive phenotype in cancer, a process characterized by a decrease in epithelial proteins such as E-cadherin, as well as an increase in mesenchymal molecules such as fibronectin and vimentin." (PMID 37566079, 2023). "Vimentin (VIM) is a protein present in cellular filaments that promotes migration of cancer cells." (PMID 37568630, 2023). "Although vimentin promotes cancer metastasis, its antitumorigenic role has been recently reported." (PMID 37371778, 2023). "Cancer cells undergoing EMT processes implicate the loss of cell polarity and lead to the transformation of the mesenchymal phenotype, accompanied by regulation of E-cadherin and the upregulation of vimentin and/or N-cadherin." (PMID 37794509, 2023). "Consequently, it seems that inhibition of the CCR2_CCL2 signaling pathway can downregulate EMT and reduces cancer progression through the inhibition of transcription factors such as Vimentin." (PMID 37325423, 2023). "Many studies have shown that melatonin can reduce vimentin expression in cancer cells." (PMID 37307404, 2023). "Furthermore, the regulation of Snail expression is associated with the expression of membrane proteins (N-cadherin and vimentin) involved in cancer cell adhesion." (PMID 38132928, 2023).